GPER1 (G protein-coupled estrogen receptor 1)
Diseases named in the same sentence as GPER1 in open-access papers (continued):
Sharing a sentence is not in itself a finding about the gene and the disease.
atherosclerosis (28 papers, 2012 to 2024). A disease characterized by the build-up of fatty material and calcium deposition in the arterial wall resulting in partial or complete occlusion of the arterial lumen. "GPER1 deficiency advances atherosclerosis progression in mice mainly by infiltrating immune cells in the vascular wall and mediated by inflammatory prostanoid production." (PMID 34746830, 2021). "In mice with pronounced atherosclerosis, GPER1 deficiency was an aggravating factor, linked to disease progression." (PMID 33133022, 2020). "Kaempferol increases the protein expression of GPER1, which, in turn, ameliorates atherosclerosis by decreasing intracellular ROS generation via the PI3K/AKT/Nrf2 pathway." (PMID 38383297, 2024). "GPER-1 is an important receptor that has been reported to have involvement in cardiovascular diseases, especially atherosclerosis." (PMID 27002821, 2016). "In summary, the present study provides the first evidence that PCA attenuates endothelial dysfunction and atherosclerosis in vitro and in vivo through activation of GPER-1." (PMID 25411835, 2014). "Thus, it is becoming increasingly difficult to ignore the importance of endothelial cells and GPER-1 in developing therapeutic agents against endothelial dysfunction and atherosclerosis." (PMID 25411835, 2014). "Additionally, GPER1 KO promotes atherosclerosis in the aorta of female mice." (PMID 35327604, 2022). "Moreover, treatment of OVX mice with G-1 attenuates immune cell infiltration and atherosclerosis, suggesting that GPER1 activation may be a therapeutic approach to target the increased cardiovascular risk in postmenopausal women." (PMID 35327604, 2022). "This suggest that the treatments of G1 and PCA can effectively down-regulate the inflammatory markers (VCAM-1 and CD40) and up-regulate GPER-1 and CD31 to attenuate atherosclerosis for both short and long term." (PMID 25411835, 2014). "Unlike PCA, GPER-1 has been consistently reported for its role in attenuating atherosclerosis because it regulates the activity of many vasoconstrictors and proliferation of vascular smooth muscle cells." (PMID 25411835, 2014). "Of particular importance is the role of GPER1 in immune cells, particularly in the antagonism of TLR4-dependent pro-inflammatory pathways, which also highlights, perhaps, a central role of NFκB-dependent signaling in pro-inflammatory vascular disease and atherosclerosis progression in particular." (PMID 34746830, 2021).
Anxiety (27 papers, 2013 to 2025). Intense feelings of nervousness, tension, or panic often arise in response to interpersonal stresses. "To contribute to a better understanding of the role of GPER1 in anxiety and stress, we investigated germ-line GPER1 deficient mice." (PMID 25236887, 2014). "Behavioral assessments revealed that Gper1KO mice displayed heightened anxiety-like behaviors and impaired spatial working memory, further emphasizing GPER1’s critical role in preserving cognitive and emotional function after TBI." (PMID 40605012, 2025). "Activation of GPER1, a novel membrane receptor for estrogen, has important roles in biological processes, such as improving learning memory and anxiety or depression behaviors in mice." (PMID 38992889, 2024). "GPER1 also mediates anxiety-like behaviour by altering the balance between GABA-ergic and glutamatergic signalling within the basolateral amygdala." (PMID 35763527, 2022). "Post hoc analysis showed that GPER1-KO exacerbated the impairment of hyperlocomotion (t = 7.873, p < 0.001) and anxiety of mice (t = 12.96, p < 0.001) with SZ induced by MK-801." (PMID 33324181, 2020). "The serum of patients with generalized anxiety disorder shows increased GPER1 levels, which correlate with the degree of anxiety." (PMID 33324181, 2020). "We recently described the induction of anxiety-like effects by the GPER1 agonist G-1 upon systemic injection into mice." (PMID 25236887, 2014). "Our data, in line with previous reports, suggest that GPER1 is involved in anxiety and stress control." (PMID 25236887, 2014). "Our data obtained from behavioral testing revealed a phenotype of sex and paradigm dependent reduced anxiety-like behavior and altered stress response in GPER1-KO mice." (PMID 25236887, 2014). "The main aim of this study was to investigate the functional role of GPER1 on anxiety and stress coping in both male and female mice." (PMID 25236887, 2014). "A study has investigated the effects of GPER1 knockdown on anxiety‐like behavior in rats and found that GPER1 knockdown resulted in anxiety‐like behavior, decreased serum corticosterone levels, and found that anxiety‐like behavior was exacerbated by SPS stimulation." (PMID 38992889, 2024). "The concentration of GPER1 in serum is higher in patients with anxiety than in the controls." (PMID 36159923, 2022). "The actions of GPER1 may also depend on the context of anxiety, i.e. whether the animal is previously stressed." (PMID 33193108, 2020). "GPER1 can regulate anxiety-related emotions, spatial learning, and memory." (PMID 33324181, 2020). "Therefore, we compared anxiety and stress coping behaviors of intact male and female WT and GPER1-KO mice in a battery of tests." (PMID 25236887, 2014). "It is tempting to speculate that there might be a reduction in anxiety paralleled by a reduction in motor activity in GPER1-KO mice." (PMID 25236887, 2014). "Our study showed that Gper1 knockout exacerbated TBI-induced cognitive dysfunction, and increased anxiety in mice." (PMID 40605012, 2025). "Unlike humans, the effect of GPER1 signaling on the anxiety-like behavior of rodents appears to be mostly anxiolytic." (PMID 36159923, 2022). "Moreover, GPER1 is involved in anxiety-like behavior; however, without displaying any clear estrogen dependency of these effects." (PMID 25236887, 2014). "Thus, GPER1 may be important in mitigating stress-induced anxiety, with little-to-no role in inhibiting behaviors that denote anxiety in the absence of stress." (PMID 33193108, 2020).
seminoma (24 papers, 2009 to 2024). A radiosensitive malignant germ cell tumor found in the testis (especially undescended), and extragonadal sites (anterior mediastinum and pineal gland). "Estrogens also promote the proliferation of the seminoma-like cell line through GPER-1 mediation via the cAMP–PKA pathway." (PMID 32899453, 2020). "Estrogen promotes the proliferation of the seminoma-like cell line through GPER-1 induction via the cAMP/PKA pathway." (PMID 32899453, 2020). "Bisphenol A, a common environmental estrogen, can also promote the proliferation of testicular seminomas cells through GPER-1." (PMID 27314054, 2016). "Estrogen induces the high expression of GPER-1 correlated with low levels of ERβ in human testicular carcinoma in situ and seminomas." (PMID 27314054, 2016). "Loss of homozygous ancestral genotype GG is more common in two polymorphisms (rs3808350 and rs3808351) in the GPER1 promoter region of spermatocytomas but not in non-seminomas." (PMID 37921845, 2023).
lung carcinoma (21 papers, 2012 to 2025). "Similar to gynecological cancers, GPER1 (over) expression in lung cancer is also associated with high TNM stage and lymph node metastasis." (PMID 39252786, 2024). "A more recent study demonstrated that, upon activation with E2 and fulvestrant, an ER inhibitor, GPER1, also stimulates the proliferation of lung carcinoma cells and tumor growth via EGFR–ERK1/2 signaling pathway." (PMID 35664735, 2022). "Previous studies have demonstrated that GPER1 is upregulated in lung cancer tissues." (PMID 38383297, 2024). "Increased GPER1 expression, especially in the cytoplasm, has been observed in lung cancer cells." (PMID 36060947, 2022). "However, in the past few years, those studies regarding anti-estrogen therapy in lung cancer generally used the fulvestrant, an antagonist for ERs, while, interestingly, an agonist for GPER1." (PMID 35664735, 2022). "On the contrary, G1, a GPER1 agonist, inhibited the proliferation and apoptosis of A549 lung cancer cells mediated by oxidant and antioxidant molecules, and suppressed the migration and angiogenesis of triple negative breast cancer cells through suppressing the NF-κB/IL-6 pathway." (PMID 33425895, 2020). "However, research focused on GPER1 in lung cancer has been scarce." (PMID 38383297, 2024). "Thus, it will be necessary considering these signaling pathways together in future studies, and to simultaneously inhibit ERs and GPER1 may provide important insight into anti-estrogen therapy in lung cancer in the future studies." (PMID 35664735, 2022). "Additionally, GPER1 is reportedly expressed in breast, ovarian, and lung cancer tissues." (PMID 36060947, 2022). "Fulvestrant can inhibit ER-related biological process, but concomitantly activate GPER1, which in turn transactivated EGFR causing cell proliferation, invasion and migration, which were demonstrated in breast, endometrial, ovarian, and recently in lung cancers." (PMID 35664735, 2022). "GPER1, in reverse, is found to enhance the phosphorylation of AKT/mTOR pathway leading to its activation in breast, ovarian and lung cancer resulting in increased cell proliferation in these types of cancers." (PMID 39252786, 2024). "Interestingly, the novel G-protein-coupled estrogen receptor 1(GPER1), which is distinct from ER−α and ER−β because it can bind E2 with high affinity and transduces rapid nongenomic signaling, has also been shown to have higher expression levels in lung carcinoma than in normal lung tissues." (PMID 35664735, 2022). "In tumor biology, GPER1 has been shown to facilitate cancer progression and migration, serving as a poor prognostic factor in ER-negative and human epidermal growth factor receptor 2 (HER2)-overexpressed breast and lung cancer cell lines." (PMID 39252786, 2024).
endometriosis (20 papers, 2012 to 2026). The growth of functional endometrial tissue in anatomic sites outside the uterine body. "Hsa-miR-151b, though not previously associated with endometriosis, has been implicated in neurological processes and may interact with GPER1, a receptor relevant to neurobiological regulation." (PMID 41501788, 2026). "A study consisting of 74 ovarian, peritoneal, and deep infiltrating endometriosis showed high cytoplasmic GPER1 expression levels in the epithelial component of endometriosis and none in the normal endometrium." (PMID 39791759, 2025).
diabetes (19 papers, 2012 to 2025). "In conclusion, GPER-1 appears to be a remarkable receptor in following up the diseaseprogression of patients with diabetes, detecting DR at an early stage, andpreventing neuronal damage." (PMID 35857982, 2022). "This analysisdetermined that GPER-1 and diabetes duration were statistically significant factorsin DR pathogenesis." (PMID 35857982, 2022). "Therefore, this study compared the serum GPER-1 levels and oxidative stress markers(malondialdehyde [MDA], catalase [CAT], and superoxide dismutase [SOD]) in patientswith diabetes and healthy individuals." (PMID 35857982, 2022).
gastric cancer (19 papers, 2019 to 2025). A primary or metastatic malignant neoplasm involving the stomach. "It has been reported that GPER1-mediated epithelial-mesenchymal transition induces cisplatin resistance in gastric cancer cells." (PMID 38383297, 2024). "In gastric cancer, GPER1 promotes gastric cancer proliferation, migration and invasion through PI3K/akt-mediated EMT." (PMID 37921845, 2023). "Meanwhile, GPER1 regulates the EMT process by blocking the PI3K-Akt signaling pathway in gastric cancer." (PMID 35677158, 2022). "GPER1 silencing inhibits gastric cancer cell proliferation, migration, and invasion via inhibiting PI3K/Akt-mediated epithelial-mesenchymal transition." (PMID 35356506, 2022). "Specifically, it has been recently shown that GPER1 knockdown or antagonism enhances the sensitivity of gastric cancer cells to Cp, suggesting that GPER1 can be a target to improve Cp chemotherapeutic efficacy against gastric tumors developing chemoresistance." (PMID 35955435, 2022). "Gene Set Enrichment Analysis was used to analyze the correlation between GPER1 expression in gastric cancer and activation of the PI3K/AKT pathway." (PMID 33425895, 2020). "We used published datasets from the Oncolnc and KM plotter database and found that gastric cancer patients with high GPER1 expression had significantly worse overall survival than patients with low GPER1 expression." (PMID 33425895, 2020). "What's more, GPER1 has been reported to induce robust EMT in cancer cells, further supporting the conclusion that GPER1 plays an important role in the EMT of gastric cancer cells." (PMID 33425895, 2020). "In this study, we used siRNA to knock down the expression of GPER1 in two gastric cancer cell lines, AGS and MGC-803." (PMID 33425895, 2020). "In summary, these data demonstrate that GPER1 inhibition suppresses the proliferation, migration, and invasion of gastric cancer cells by inhibiting PI3K/AKT-mediated EMT." (PMID 33425895, 2020). "Our data demonstrate that knockdown of GPER1 suppressed the proliferation of gastric cancer cell lines." (PMID 33425895, 2020). "ESR1, ESR2, and GPER1 mRNA expression data of all gastric carcinoma cell lines were downloaded from the Broad Institute Cancer Cell Line Encyclopedia (CCLE2) and analyzed on Morpheus3." (PMID 33553141, 2020). "In the process of seeking the potential value of GPER1 as a therapeutic target in gastric cancer." (PMID 33425895, 2020). "The PI3K activator, 740Y-P, could partially reverse the effects of GPER1 knockdown on the migration and invasion of gastric cancer cells." (PMID 33425895, 2020). "GPER1 expression is associated with poorer prognosis in patients with gastric cancer, but the specific role of GPER1 in gastric cancer development and progression is not well-understood." (PMID 33425895, 2020). "However, whether the GPER1 contributes to gastric cancer progression and metastasis through a mechanism involving the PI3K pathway and EMT remains unclear." (PMID 33425895, 2020). "Our findings suggest that GPER1 may represent a novel target in the treatment of gastric cancer." (PMID 33425895, 2020). "These research outcomes align with our findings of elevated GPER1 expression being correlated with adverse prognosis in STAD, indicating its potential as a therapeutic target for gastric cancer treatment." (PMID 37921845, 2023). "Then we examined the expression of GPER1 by western blot in four gastric cancer cell lines, including MGC-803, AGS, BGC-823, and MKN-45 and found that GPER1 was highly expressed in the AGS and MGC-803 cell lines." (PMID 33425895, 2020). "In the current study, we found that silencing of GPER1 inhibited the EMT by upregulating E-cadherin and downregulating N-cadherin and vimentin, resulting in a decline in the migration and invasion of gastric cancer cell lines." (PMID 33425895, 2020).
gastric cancer (continued). "We showed that knockdown of GPER1 downregulated the PI3K/AKT pathway, thereby inhibiting EMT and suppressing the migration and invasion of gastric cancer cells." (PMID 33425895, 2020). "In conclusion, our study demonstrated that knockdown of GPER1 blocked EMT in gastric cancer cells by inhibiting the PI3K/AKT pathway, leading to inhibition of proliferation, migration, and invasion of gastric cancer cells." (PMID 33425895, 2020). "However, the functional role of GPER1 in gastric cancer (GC) remain incompletely understood." (PMID 33425895, 2020). "The combined targeting of GPER1 and the PI3K/AKT pathway may serve as a novel therapeutic strategy for gastric cancer." (PMID 33425895, 2020). "Our study elucidated the function of GPER1 in gastric cancer, and we identified PI3K/AKT-mediated EMT as a novel mechanism by which GPER1 contributes to proliferation, migration, and invasion of gastric cancer." (PMID 33425895, 2020). "The roles of GPER1 in gastric cancer (GC) have not been fully clarified." (PMID 33425895, 2020).
ischemia (19 papers, 2010 to 2025). A hypoperfusion of the BLOOD through an organ or tissue caused by a PATHOLOGIC CONSTRICTION or obstruction of its BLOOD VESSELS, or an absence of BLOOD CIRCULATION. "The expression of GPER1 began to increase after 6 h of ischemia, reached a peak at 48 h, and began to decrease at 72 h after global cerebral ischemia in rats." (PMID 40605012, 2025). "Obviously, GPER1 is part of a complex calcium signaling machinery, and its upregulation arbitrates cardio-protection following doxorubicin-induced ischemia, oxidative stress and apoptosis." (PMID 39285385, 2024). "In primary neocortical cell cultures subjected to 18 h of ischemia followed by a 6 h reoxygenation period, we observed a significant increase in Esr2 and Gper1 mRNA expression (2.33- and 4.24-fold, respectively)." (PMID 37129835, 2023). "The only GPER1-induced effect was directed at astrocyte death due to the rise in intracellular calcium levels during ischemia." (PMID 36835454, 2023). "Inhibition of apoptotic activity and inflammation, improvement of mitochondrial function, and regulation of nitric oxide synthase have been proposed as mediators of GPER1-protective actions against ischemia reperfusion injury in different organ systems." (PMID 35955435, 2022). "Furthermore, GPER1 distribution was increased in the peri-infarct brain regions of male mice, but was decreased in the infarct core of both sexes of mice subjected to ischemia–reperfusion." (PMID 36835454, 2023). "Moreover, ospemifene (10 μM) normalized the levels of ESR2 diminished in response to both hypoxia and ischemia as well as normalized the GPER1 level elevated in response to ischemia." (PMID 37129835, 2023). "The beneficial effects of ER agonists, particularly estrogens, on brain tissue undergoing hypoxia and/or ischemia have been extensively reported; however, only a few research reports have focused on membrane ERs, mainly GPER1 (previously GPR30)." (PMID 34797527, 2021).
colon carcinoma (18 papers, 2017 to 2025). "GPER1 expression has been also implicated in gastric and colon cancers, in which its downregulation is associated with poor prognosis." (PMID 37759449, 2023). "Pre-treatment with NF449 or the adenylyl cyclase inhibitor SQ 22,536 before GPER1 activation restored elevated cAMP to baseline levels, confirming a GPER1-Gαs-adenylyl cyclase signaling axis in our colon cancer cell system." (PMID 41299155, 2025). "Here, we show that PKA is central to a signaling cascade involving the G protein-coupled estrogen receptor GPER1, which is essential for centrosome integrity in colon cancer cells." (PMID 41299155, 2025). "Because the role of GPER1 in colon cancer development is still under debate, future studies are needed demonstrating to what extent centrosomal proteins are involved in the GPER1-mediated aneugenic effect observed in this colon (cancer)-derived study." (PMID 36384894, 2023). "In other male-dominant gastrointestinal tumors, the expression levels of GPER1 in gastric and colon cancers were lower than those in their corresponding normal tissues, and patients with low levels of GPER1 showed significantly poorer survival rates compared with those with greater levels of GPER1." (PMID 37762356, 2023). "Collectively, our findings provide compelling evidence for the involvement of the GPER1-PKA-Centrin-2 axis in regulating centrosome numbers and centriole integrity in a colon cancer-derived in vitro model." (PMID 41299155, 2025).